CCND1 (cyclin D1)
Diseases named in the same sentence as CCND1 in open-access papers (continued):
Sharing a sentence is not in itself a finding about the gene and the disease.
colorectal cancer (continued). "A study on colorectal cancer showed that reduced expression of HNF1A-AS1 inhibited Wnt/β-catenin activity by downregulating the expression of β-catenin, cyclin D1, and CMYC." (PMID 38654006, 2024). "SAE1 knockdown inhibited cell proliferation in vitro and in vivo, decreased the protein expression of cyclin D1, increased PARP protein expression, and promoted radiosensitivity in colorectal cancer cells." (PMID 37886949, 2023). "IRS4 is overexpressed in colorectal cancer, and when overexpressed in RKO cells, it induces the expression of cyclin D1, Cyclin E, E2F1, and pRB Ser 705 and pRB Ser809/811 genes." (PMID 37686244, 2023). "Database analysis revealed the expressions of VEGFA, CCND1, and YTHDF1 were all upregulated in colorectal cancer tissues compared with the normal cohort." (PMID 38001065, 2023). "Consistently, kinetin riboside repressed expression of c-Myc and cyclin D1, β-catenin/T-cell factor (TCF)-dependent genes, and inhibited the proliferation of colorectal cancer cells." (PMID 37463866, 2023). "It has been reported that SIRT4 is decreased in colorectal cancer (CRC) and exerts inhibitory effects by targeting GLS-mediated AKT/GS3β/cyclin D1." (PMID 35847357, 2022). "And our study focused on the mechanism of DDX39B in the proliferation of colorectal cancer, we found that DDX39B can bind directly to the exons of CCND1/CDK6 mRNA to upregulate their expression and promote the CRC cell proliferation as an oncogene." (PMID 35046400, 2022). "Overexpression of miR-449a significantly suppress the progression of colorectal cancer by affecting the expression of target genes LEF-1 and cyclin D1." (PMID 36545680, 2022). "This phenotype demonstrated that not only overexpression of DDX39B can promote the proliferation of the colorectal cancer cells but also that can be reversed after knockdown of the CDK6 and CCND1." (PMID 35046400, 2022). "Activation of the Wnt/β-catenin signaling pathway drives colorectal cancer growth by deregulating the expression of many downstream targets, such as c-JUN, c-Myc, cyclin D1, CD44 and Axin2." (PMID 35065674, 2022). "For example, CDCA2 modulates cyclin D1 expression as a result of PI3K/AKT pathway activation; thus, promoting the development of colorectal carcinoma cells." (PMID 34082692, 2022). "The prior studies have revealed that Cyclin D1 and CDK6 were abundantly expressed in colorectal cancer and have attracted much attention in multiple areas of cancer research and prognosis judgement." (PMID 33726765, 2021). "For example, in colorectal cancer, CDCA3 can mediate p21-dependent proliferation by regulating E2F1 expression or promote cell proliferation by activating the NF-KappaB /cyclin D1 signaling pathway." (PMID 34430085, 2021). "In colorectal cancer, up-regulation of LINC00467 reduces the expression of cyclin A1, cyclin D1, CDK2, CDK4 and Twist1, and enhances the expression of E-cadherin, thus promoting the development of colorectal cancer." (PMID 34888249, 2021). "In colorectal cancer, CD73 downregulated cell growth via EGFR and the β-catenin/cyclin D1 signalling pathway." (PMID 33187081, 2020). "For example, high copy numbers of ERBB2, TOP2A, CCND1, EGFR and MYC are observed in many colorectal cancers." (PMID 31009485, 2019). "Further western blotting results showed that the endogenous Wnt responder gene expression of cyclin D1, c-Myc, and Axin2 was suppressed in HT29, HCT116, and SW480 colorectal cancer cells treated with 4βHWE." (PMID 30909473, 2019). "Astragaloside IV significantly inhibits the expression of several key cell cycle-related proteins (Cyclin D1 and CDK4) in colorectal cancer cell lines." (PMID 30832202, 2019). "Genes known to be dysregulated in colorectal cancers, such as MYC and CCND1, were also found to be highly and significantly up-regulated in our RNA-seq analysis, which was further validated by RT-qPCR analysis." (PMID 32082365, 2019).
colorectal cancer (continued). "Because cyclin D1 not only induces over-proliferation of cancer cells, but also regulates apoptosis, and increased cyclin D1 protein level is observed in human colorectal cancer, the effect of STL and STB on cyclin D1 level was investigated." (PMID 30736789, 2019). "In our study, Western blot showed that Rg3 reduces the expression of NF-κB-regulated gene products (cyclin D1, survivin, and COX2) in cancer cells, indicating that Rg3 enhances radiosensitivity of colorectal cancer." (PMID 29743919, 2018). "The results revealed that Cyclin D1, Cyclin D2, CDK4 and CDK6 were all decreased in si-SNHG1-transfected colorectal cancer cells." (PMID 30266084, 2018). "It was particularly noticed by Jeong and colleague that PCA can potently inhibit growth of colorectal cancer cells with suppression of HDAC2 and Cyclin D1 expression." (PMID 29285297, 2017). "Lactobacillus reuteri was shown to prevent colorectal cancer via downregulating NF-kB-dependent gene products that regulate cell proliferation (COX-2, cyclin D1) and survival (Bcl-2, Bcl-xL)." (PMID 26849051, 2016). "Among these miRNAs, miR-497 is down-regulated in breast, gastric, and colorectal cancer and promotes cell proliferation and invasion by up-regulating raf-1/Ccnd1, EIF4E, and insulin growth factor 1 receptor in breast, gastric, and colorectal cancer." (PMID 27531900, 2016). "In the current study, we evaluated the effect of the ethanol extracts from PF on cyclin D1 and CDK4 suppression in the colorectal cancer cells." (PMID 27670681, 2016). "Next, the mRNA expression of several important β-catenin target genes, including c-myc, cyclin D1, and CD44, was examined by Q-PCR in breast and colorectal cancer cells." (PMID 27779255, 2016). "The data presented herein have shown that the G1 phase cyclin D1, D2, D3, CDK4, CDK6 and pRB proteins are highly expressed in colorectal carcinoma tissues as compared to the matched adjacent normal colorectal tissues." (PMID 24765199, 2014). "The results revealed dose-dependent and time-dependent reductions in the expression of a range of cell cycle proteins, including cyclin E1, cyclin D1, and CDK6, accordingly indicating that CS&Z can influence the progression of the cell cycle in colorectal cancer cells." (PMID 40429805, 2025). "The PI3K/AKT pathway plays a pivotal role in the onset and progression of colorectal cancer, influencing autophagy, apoptosis, and EMT-mediated cancer cell migration and invasion, accompanied by regulation of CCND1, mTOR, FOXO, HIF-1α, CASP, Bax, and Bcl-2 expression." (PMID 38384287, 2024). "In colorectal cancer cells, STAT3 can directly target the promoter of cyclin D1." (PMID 37701157, 2023). "In human colorectal cancer cell lines (HCT116, HT-29, SW620, and DLD-1) ergosterol peroxide derived from Chaga, induced cell cycle arrest by reducing transcription of c-Myc, CDK-8, and cyclin D1 with increasing apoptosis induction." (PMID 37153767, 2023). "Moreover, another study on colorectal cancer found that ZC3H13 inhibits tumor cell proliferation and invasion by downregulating the expression of Snail, cyclin D1 and cyclin E1 by inhibiting the RAS signaling pathway." (PMID 35223847, 2022).
colorectal cancer (continued). "A previous study showed that ATG4B knockdown increased CCND1 expression and resulted in colorectal cancer cell growth arrest independent of autophagy." (PMID 35184132, 2022). "Moreover, another study suggested that in colorectal cancer, HOXB7 accelerated G0-G1 to S-phase transition concomitantly with upregulation of cyclin D1 and downregulation of p27Kip1 in tumor cells." (PMID 34303375, 2021). "Similarly, colorectal cancer cells transfected with ESM1 siRNA resulted in cell cycle arrested at G1 phase by inducing PTEN and inhibition of cyclin D1." (PMID 28108731, 2017). "To investigate the effect of hypoxia on Wnt/β-catenin signaling in colorectal-cancer cells, we thus examined the quantitative changes in the expression of positive (Wnt1, Lef1, cyclin D1) regulators of Wnt/β-catenin signaling with or without hypoxia." (PMID 26965643, 2016). "Furthermore, EOPK significantly decreased proliferation and migration, induced G1-arrest, and inhibited the expression of phospho-ERK, phospho-AKT, β-catenin, cyclin D1 and CDK4/6 in colorectal cancer cells." (PMID 25074784, 2014). "PPARγ ligand treatment not only decreases the protein level of cyclin D1, but also increases the CDK inhibitors p21CIP and p27KIP1 through both increased transcriptional activity and inhibition of proteasome degradation in colorectal cancer cells." (PMID 23024650, 2012). "We analyzed the influence of 8 germinal polymorphisms of candidate genes potentially related to EGFR signalling (EGFR, EGF, CCND1) or antibody-directed cell cytotoxicity (FCGR2A and FCGR3A) on outcome of colorectal cancer (CRC) patients receiving cetuximab-based therapy." (PMID 22117530, 2011). "Thus, there was a negative correlation of the amount of MG53 and cyclin D1 in cultured cancer cells and tumors derived from animal models as well as patients with gastric or colorectal cancers." (PMID 37414783, 2023). "In the current study, we found that roburic acid could significantly downregulate Cyclin D1 and c-Myc protein levels in colorectal cancer cells, with or without TNF stimulation." (PMID 35222445, 2022). "A study showed that the expression of PCNA, Cyclin-D1, MMP-2, and MMP-9 genes can induce the formation of colorectal cancer and promote cancer cell proliferation, migration, and invasion, suggesting that these genes may be closely related to cell proliferation and migration." (PMID 32733959, 2020). "It has been previously reported that Daxx regulates the expression of cyclin D1 at the transcription level in colorectal cancer and that cyclin D1 is important for OSCC growth activity; we therefore tested whether Daxx can regulate cyclin D1 expression in OSCC using OSCC cell line." (PMID 26205068, 2016). "The G1 phase‐related gene cyclin D1 was downregulated while the cell cycle inhibitor Rb1, Rbl1, and P21 were upregulated by inhibition of GABABR, which helped us determined that activation of GABABR can significantly promoted colorectal cancer cell proliferation by arrested cell at G1 phase." (PMID 27060477, 2016). "PPARβ/δ expression levels in colorectal cancers are higher than in normal mucosa, supporting the hypothesis that APC suppresses activity of β-catenin/Tcf-4 transcription of target genes, including PPARβ/δ, c-myc, and cyclin D1." (PMID 23024650, 2012). "In line with our observation, it has been reported that in the absence of distinct TCF7L2 variants the regulation of common TCF/LEF target genes such as cyclin D1, c-myc, MMP7 and c-jun is not detectable in renal cell carcinoma and colorectal cancer cell lines." (PMID 21281469, 2011).
hepatocellular carcinoma (263 papers, 1999 to 2026). A malignant tumor that arises from hepatocytes. "Melatonin by influencing cell cycle-related proteins, such as decreasing the expression of cyclin D1, causes the inhibition of the proliferation and induces cell cycle arrest of HepG2 and Hep3B cell line of hepatocellular carcinoma (HCC)." (PMID 36759799, 2023). "The aim of this study is to explore the underlying mechanism on berberine-induced Cyclin D1 degradation in human hepatic carcinoma." (PMID 27854312, 2016). "In this study, the underlying mechanism of Cyclin D1 suppression by berberine in human hepatoma cells was examined." (PMID 27854312, 2016). "We assessed the immunoreactivity levels of SHP and cyclin D1 in 48 typical hepatocellular carcinomas, 9 tumors representing the fibrolamellar variant, 29 non malignant liver tissues and 7 macroregenerative nodules." (PMID 22292081, 2012). "Ectopic expression studies of miR-195 caused G1/S phase block by targeting cyclin D1 whereas miR-101-1 dramatically suppresses the ability of hepatoma cells to form colonies and develop tumours." (PMID 22035408, 2011). "We observed rapid loss of cyclin D1 protein upon GGA treatment in several human hepatoma cell lines (HuH-7, PLC/PRF-5, and HepG2) and reported that the mechanism is not transcriptional regulation of the cyclin D1 (CCND1) gene but the rapid arrest of its translation." (PMID 37247782, 2023). "Similarly for the pan-Akt inhibitor, MK2206, studies have demonstrated that treatment with this drug induced G0/G1-phase arrest which was associated with a marked decrease in cyclin D1 levels in hepatocellular carcinoma HepG2 cells." (PMID 30056610, 2019). "In addition, loss of HDAC5 restrains the cell proliferation of hepatocellular carcinoma by regulation of p21 and cyclin D1, thereby leading to cell cycle arrest and apoptosis." (PMID 25546298, 2014). "In particular, it was noticed that Cyclin D1 was overexpressed in hepatocellular carcinoma (HCC) and was associated with aggressive forms of HCC." (PMID 27854312, 2016). "Overexpression of zinc finger protein 384 (ZNF384), a poor prognostic predictor, has been found to promote cell growth by upregulating the expression of Cyclin D1 in hepatocellular carcinoma." (PMID 40599863, 2025). "In hepatocellular carcinoma (HCC), ZFP36 functions as a tumor suppressor by destabilizing oncogenic mRNAs such as PRC1, CCND1, and CDK6, which are implicated in cell cycle progression and tumor growth." (PMID 40361912, 2025). "Hexachlorobenzene activates the ERK1/2 signaling pathway in an AhR-dependent manner, upregulates the expression of the cell cycle protein Cyclin D1, and promotes the proliferation of hepatocellular carcinoma cells and hepatic preneoplastic lesions." (PMID 41585883, 2025). "In conclusion, our findings revealed that WISP1 suppresses hepatoma cell proliferation through the downregulation of Cyclin D1 protein levels." (PMID 39763353, 2024). "In hepatocellular carcinoma, silencing BRD4 or MED1 repressed the transcription of SE-associated genes like SPHK1, E2F2, CCND1, MYCN, and MYC." (PMID 38443991, 2024). "For example, in hepatocellular carcinoma, the downregulation of DNM3 promoted cell proliferation by increasing cell cycle-associated proteins, including cyclin D1, and the upregulation of DNM3 induced cell apoptosis and inhibited tumor growth." (PMID 38742190, 2024). "E2F8 is involved in the regulation of cyclin D1 and promotes the accumulation of S-phase cells in hepatocellular carcinoma, further highlighting its role in cell proliferation." (PMID 39061176, 2024). "JCAD knockdown by siRNA in Huh‐7 and Huh‐7‐trans cells, the latter is a high‐metastatic hepatoma cells derived from Huh‐7 cells, resulted in down‐regulation of cyclin D1 at both mRNA and protein levels." (PMID 38509842, 2024).
hepatocellular carcinoma (continued). "Significantly, the overexpression of WISP1 in hepatoma cells leads to enhanced ubiquitination and subsequent degradation of the Cyclin D1 protein, further elucidating the molecular mechanisms underlying HCC cell proliferation inhibition." (PMID 39763353, 2024). "To determine if WISP1 suppresses hepatoma cell proliferation through the modulation of cyclin D1, we introduced an overexpression of WISP1 in these cells using the WISP1-his plasmid." (PMID 39763353, 2024). "Previous studies showed that MCM2 and MCM7 promote hepatocellular carcinoma cell stemness and tumor progression via hippo signaling and cyclin D1-dependent signaling, respectively, and overexpression of them correlates with poor prognosis in HCC." (PMID 38343446, 2023). "These authors have also shown that VRK1 plays a crucial role in G1/S transition and that its depletion induces a G1 arrest by downregulating cyclin D1 and phospho-RB, and upregulating P21 and P27 in hepatocellular carcinoma." (PMID 37886173, 2023). "The Wnt/β-catenin signaling pathway drives the expression of the downstream key target gene CCND1 and was found to play an important role in the occurrence and development of hepatocellular carcinoma, being necessary for proliferation." (PMID 37951919, 2023). "Many acetogenins supposedly regulate the cell cycle to the G1/S transition checkpoint by inhibiting cyclin D1 expression in human hepatocellular carcinoma cells." (PMID 37627523, 2023). "EGCG significantly reduces the expression of cyclin D1 protein in hepatoma cells, which leads to cell cycle arrest, especially when combined with metformin." (PMID 37292151, 2023). "Enforced overexpression of MafB promotes hepatocellular carcinoma proliferation by enhancing cyclin D1." (PMID 36750911, 2023). "It is known that a variety of cell cycle proteins play a key role in hepatocellular carcinoma, such as Cyclin D1 (CCND1), C-myc or Ras, cyclin D2 (CCND2), etc.." (PMID 37400985, 2023). "A positive cell cycle regulatory effect of AKT is reported to prolong the activation of the cell cycle regulator cyclin D1 (CD1) in hepatocellular carcinoma." (PMID 35215343, 2022). "We also found that the expression of CDK1 and CCND1 was upregulated in HepG2 hepatoma cells following a 2.5 μM arecoline treatment." (PMID 35836300, 2022). "CCND1 inhibition, regulated by miR-144, can significantly inhibit the proliferation, migration and invasion of hepatoma cells." (PMID 35836300, 2022). "The anti-tumor effects of ultrasound-targeted microbubble destruction-delivered si-CCND1 were elicited via blockage of the PI3K/AKT pathway in hepatocellular carcinoma." (PMID 35246017, 2022). "Synthesis of DNA and contact-independent growth in several human cancers including hepatocellular carcinoma (HCC) can be enhanced when cyclin D1 is overexpressed." (PMID 35774605, 2022). "This was supported by a previous study which showed that Mini-chromosome maintenance complex component 7 up-regulates cyclin D1 through modulating MAPK signaling in hepatocellular carcinoma." (PMID 35834029, 2022). "Next, to further validate the effect of miR‐106b‐5p on Ccnd1 we transduced two human liver carcinoma cell lines (Mahlavu and HepG2) with this miRNA and measured the mRNA levels of its target gene." (PMID 35174557, 2022). "Specifically, CTBP1-AS2 can facilitate hepatocellular carcinoma cell proliferation by regulating the miR-623/Cyclin D1 axis." (PMID 35039872, 2022). "For instance, PRDX2 enhances the proliferation and tumorigenicity of hepatoma cells by regulating the ERK/FoxM1/cyclin D1 signal axis." (PMID 34384442, 2021). "OCT4 can upregulate the expression of BIRC5 and CCND1 by enhancing its promoter activity, these factors jointly promote the proliferation of liver cancer cells and aggravate prognosis of patients with Hepatocellular Carcinoma (HCC)." (PMID 34087900, 2021).